USE1 (unconventional SNARE in the ER 1)
Description:
SNARE that may be involved in targeting and fusion of Golgi-derived retrograde transport vesicles with the ER.
Synonyms: MDS032; p31; SLT1; D12
Tractability: Antibody: UniProt predicts a signal peptide or a membrane-spanning region. PROTAC: ubiquitination databases record sites on it; its protein half-life has been measured.
Gene: Protein-coding gene on chromosome 19 (17,215,346 to 17,220,237, forward strand). Ensembl gene ENSG00000053501.
Subcellular location: Endoplasmic reticulum membrane
Pathways (Reactome):
Vesicle-mediated transport: COPI-dependent Golgi-to-ER retrograde traffic
Gene Ontology:
Molecular function: protein binding; SNAP receptor activity
Biological process: endoplasmic reticulum to Golgi vesicle-mediated transport; lysosomal transport; protein catabolic process; retrograde vesicle-mediated transport, Golgi to endoplasmic reticulum; secretion by cell; membrane fusion
Cellular component: endoplasmic reticulum; endoplasmic reticulum membrane; lysosome; SNARE complex; COPI-coated vesicle
Genetic constraint (gnomAD): Loss-of-function variants: 32 observed, 36.19 expected, observed/expected ratio (o/e) 0.88, 90% interval 0.67 to 1.19. The upper end of that interval is the gene's LOEUF score, 1.19, which puts it in group 5 of 6, group 1 being the genes least tolerant of losing a copy. Missense variants: 310 observed, 328.71 expected, observed/expected ratio (o/e) 0.94, 90% interval 0.86 to 1.04. Synonymous variants: 149 observed, 137.43 expected, observed/expected ratio (o/e) 1.08, 90% interval 0.95 to 1.24.
Homologues: Orthologues: macaque USE1 (98% identical), pig USE1 (95% identical), rat Use1 (89% identical), mouse Use1 (88% identical), dog USE1 (86% identical), chimpanzee USE1 (83% identical), guinea pig USE1 (83% identical), tropical clawed frog use1 (69% identical), zebrafish use1 (64% identical), Drosophila melanogaster Use1 (30% identical), Caenorhabditis elegans use-1 (26% identical).
Diseases named in the same sentence as USE1 in open-access papers:
USE1 is named in the same sentence as 13 diseases in open-access papers, as found by Europe PMC text mining. Sharing a sentence is not in itself a finding about the gene and the disease. The quoted sentences say what the papers report.
lung carcinoma (2 papers, 2019 to 2024). "Although there was indirect evidence, enhanced expression of USE1 was revealed in lung cancer and its mutation was involved in tumor formation." (PMID 38474091, 2024). "The overexpression of USE1 promoted the proliferation, migration, and invasion of lung cancer cell lines, whereas the knockdown of USE1 markedly reduced these phenomena." (PMID 31067743, 2019). "Enhanced invasive property was revealed in USE1-overexpressed lung cancer cells." (PMID 38474091, 2024). "However, more evidence needs to be found to elucidate whether the overexpression of USE1 exerts its function by modulating proteostasis in lung cancer cells." (PMID 31067743, 2019).
myocardial infarction (1 paper, 2019). Gross necrosis of the myocardium, as a result of interruption of the blood supply to the area, as in coronary thrombosis. "USE1 mRNA was differentially expressed in myocardial infarction (MI)." (PMID 31067743, 2019).
pancreatic cancer (1 paper, 2025). "Among the previously known and here confirmed interactors (CDH1, DISP1, SCFD1, USE1, TSG101, and USP8), CDH1 (E‐cadherin), a critical adhesion molecule, is frequently lost or downregulated in pancreatic cancer, promoting epithelial‐to‐mesenchymal transition (EMT) and enhancing tumor invasiveness." (PMID 40952239, 2025).
infection (4 papers, 2022 to 2025). The state of being infected such as from the introduction of a foreign agent such as serum, vaccine, antigenic substance or organism. "We found that USE1 and ZW10 expression was significantly increased in infected Calu3 cells at 9 h post-infection compared to the previous time points, and RINT1 had a similar trend." (PMID 36768954, 2023). "A549 cells treated with siRNA directed against BET1 or USE1 or with negative control siRNA (siBET1, siUSE1, or siNC, respectively) were infected with rMuV/AcGFP at a multiplicity of infection (MOI) of 0.05." (PMID 36480520, 2022).
tumor (4 papers, 2019 to 2025). "Other genes down-regulated in ATRX-altered tumours included USE1, SULT4A1 and the nuclear-encoded mitochondrial gene COX17." (PMID 38978571, 2024).
cancer (1 paper, 2019). A tumor composed of atypical neoplastic, often pleomorphic cells that invade other tissues. "The unchanged mRNA level suggests an increased translation or decreased degradation of the USE1 protein in cancer tissues." (PMID 31067743, 2019). "It remains unclear how USE1 exerts its functions in cancer cell lines." (PMID 31067743, 2019).
USE1 also shares sentences with these, for which no sentence is quoted: melanoma (2 papers); acute renal failure (1); epilepsy (1); myopia (1); nutritional deficiency (1); Obesity (1); Sepsis (1).